CXCR4 (C-X-C motif chemokine receptor 4)
Diseases named in the same sentence as CXCR4 in open-access papers (continued):
Sharing a sentence is not in itself a finding about the gene and the disease.
osteosarcoma (continued). "Thus far, there is insufficient evidence on the role of 68Ga-Pentixafor in osteosarcoma; however, from the published data on immunohistochemistry, this tracer may have a role in prognosis and selecting patients who may benefit from therapies targeting CXCR4." (PMID 36140541, 2022). "Therefore, we performed this meta-analysis to identify studies from published literature and to evaluate whether expression of CXCR4 in patients with osteosarcoma can be a suitable prognostic and histopathological marker in the correlation to overall survival and clinicopathological features." (PMID 36816176, 2022). "While the CXCL12/CXCR4 signaling stimulates Akt phosphorylation, the use of the Akt inhibitor AKTi-1/2 decreased CXCL12 and CXCR4 mRNA levels in human 143B and murine MOTO osteosarcoma cell lines." (PMID 34440844, 2021). "hBMMSCs also enhance osteosarcoma and HCC cell migration and invasion by activating the AKT and ERK pathways of tumor cells via CXCR4." (PMID 33849537, 2021). "In osteosarcoma, UCA1 knockdown inhibits miR-301a expression and induces the silencing of C-X-C chemokine receptor type 4 (CXCR4), thus decreasing cell proliferation and metastasis." (PMID 33777227, 2021). "Further, CXCR4-YY1 reciprocal regulation has been well documented as a pro-tumorigenic function of CXCR4 in AML therapy resistance and osteosarcoma angiogenesis." (PMID 33966046, 2021). "In osteosarcoma, inhibition of UCA1 downregulates miR-301a expression and decreases CXCR4 expression, thus suppressing cell proliferation and metastasis." (PMID 33777227, 2021). "Current study is focused on the immunohistochemically analysis of CXCR4 and CD133 expression in osteosarcoma as the most frequent types of adult and pediatric sarcomas." (PMID 31983166, 2020). "In osteosarcoma, the interaction between chemokine CXCL12 and its receptor CXCR4 drives the metastasis of osteosarcoma cells to the lung." (PMID 32974202, 2020). "The clinical data from a total of 98 cases with osteosarcoma and the corresponding expression data of CXCR2, CXCR3, CXCR4, and CXCR5 were included." (PMID 31696204, 2019). "In osteosarcoma cells, miR-302a inhibits cell migration and invasion by directly targeting IGF-1R, and miR-302a can target GAB2, CXCR4, SDF1, Cyclin A, and Cyclin D to suppress cell proliferation, migration and invasion in glioma." (PMID 30765768, 2019). "Based on the available data of CXCRs in osteosarcoma, we assessed the prognostic role of CXCR2, CXCR4, and CXCR5 expression in osteosarcoma." (PMID 31696204, 2019). "The Kaplan–Meier analyses were conducted to estimate the survival impact of expression of CXCR2, CXCR3, CXCR4, and CXCR5 in osteosarcoma." (PMID 31696204, 2019). "Previous study reported that IL-17A and IL-17R interaction enhanced the metastasis of osteosarcoma cells via the expression of VEGF, MMP-9 and CXCR4." (PMID 26850593, 2016). "In FOXC2 knockdown cell lines, we show that CXCR4, a downstream target of FOXC2, can restore osteosarcoma cell invasiveness and metastasis to the lung." (PMID 27634875, 2016). "The C-X-C motif chemokine 12/C-X-C chemokine receptor type 4 (CXCL12/CXCR4) signaling axis is involved in the development of tumors and the metastatic spread of various cancer types, including osteosarcoma." (PMID 26622806, 2015). "The binding to representative osteosarcoma cells (F5M2 and F4 for high- and low- CXCR4 expression) was examined." (PMID 26472699, 2015). "The two cell lines were derived from the same parental osteosarcoma cell line SOSP-960719, suggesting that difference in CXCR4 expression is responsible for binding difference." (PMID 26472699, 2015). "Having demonstrated that hypoxia-induced CXCR4 expression was regulated by HIF-1α in osteosarcoma cell lines, we next investigated the correlation between CXCR4 and HIF-1α expression in 98 osteosarcoma cases." (PMID 24618817, 2014).
osteosarcoma (continued). "CXCR4, the receptor of the chemokine CXCL12, has been reported to promote tumor progression and metastasis in osteosarcoma." (PMID 24040160, 2013). "The CXCR4 inhibitors T134 peptide and CTCE-9908 have both been shown to decrease or prevent the development the osteosarcoma metastases in mice." (PMID 21234386, 2011). "Both mouse and human DP osteosarcoma cells had increased expression of ABCG2 and CXCR4 compared to DN cells." (PMID 20979639, 2010). "Ghost cell lines (Human osteosarcoma cells) expressing CCR5, CXCR4 with CD4 or CD4 alone (received from NIH AIDS Reagent Program) were used to determine co-receptor use." (PMID 19939258, 2009). "Human osteosarcoma cells modified to express CD4 and CXCR4 (HOS-CD4/CXCR4) support robust HIV-1 replication, which is potently restricted by pre-treatment with IFNβ." (PMID 18389079, 2008). "CCR1, CCR2, CCR5, CCR7, CXCR4, CXCR5 and CX3CR1 were found to be expressed in 100% of the osteosarcoma samples tested." (PMID 18215331, 2008). "They used the CXCR4 antagonist AMD3100 to block the binding of SDF-1 to CXCR4, which significantly reduced the infiltration of MDSCs in osteosarcoma and had a synergistic effect when combined with anti-PD-1 antibodies, a novel option for immunotherapy of osteosarcoma." (PMID 39916962, 2024). "In fact, although Cxcr4 is required for osteoblastic differentiation, it also seems to intervene, together with YY1 and VEGF, in the pathogenesis of the malignant phenotype of osteosarcoma by promoting cell invasiveness and metastasis." (PMID 34638956, 2021). "Moreover, we also evaluated the possible relationship of CXCR4 and CD133 expression in osteosarcoma samples." (PMID 31983166, 2020). "Forced re-expression of CXCR4 in the 143B FOXC2 knockdown cells restored their invasive capabilities in vitro and in vivo, indicating that CXCR4 is a downstream target and a functional mediator of FOXC2 signaling in osteosarcoma." (PMID 27634875, 2016). "In addition, conditioned medium from BMSCs can promote the proliferation and invasion of osteosarcoma cells, and AMD3100, an antagonist for CXCR4, can significantly downregulate these growth-promoting effects." (PMID 25890096, 2015). "BMSCs can promote the proliferation and invasion of osteosarcoma cells, which may involve the SDF-1/CXCR4 axis." (PMID 25890096, 2015). "However, in our study, hypoxia upregulated the transcription of the CXCR4 gene by enhancing the transcription factor HIF-1α and thus promoted cell migration in human osteosarcoma." (PMID 24618817, 2014). "We performed immunohistochemistry, immunocytochemistry, quantitative real-time PCR, Western blots and fluorescent reporter assays to evaluate the correlation between CXCR4 and HIF-1α expression in human osteosarcoma specimens or SOSP-9607 cells under normoxic and hypoxic conditions." (PMID 24618817, 2014). "Among CXCR4 inhibitors, AMD3100 is in clinical use for leukemia, and CTCE-9908 was granted approval by the FDA for osteosarcoma based on its potent inhibitory activity in preclinical models of osteosarcoma." (PMID 24472670, 2014). "The cell line is derived from human osteosarcoma (HOS) cells by stable transduction with HIV-2 long terminal repeat (LTR)-driven green fluorescent protein (GFP) reporter, human CD4 receptor, and human CXCR4 chemokine receptor genes." (PMID 17565699, 2007). "While the tumor tissue used to assess survival was obtained from sites of primary disease as opposed to to metastatic sites, these data indicate that CXCR4 is of potential clinical relevance and should be further investigated in the context of metastatic osteosarcoma." (PMID 39896512, 2025). "The results obtained with osteosarcoma cells were confirmed for HeLa cells in which we found a higher expression of the CXCR4 stem cell marker, a higher SP fraction in cells overexpressing RAB39A, and a reduced CXCR4 expression and SP fraction in cells with knockdown of RAB39A." (PMID 29515775, 2018).
osteosarcoma (continued). "There were a small number of recent studies reporting prognostic biomarkers for osteosarcoma which were associated with lung metastases and survival such as PLA2G16, MMP-2, CXCR4 and MMP9, but none of them showed correlation with response to chemotherapy treatment." (PMID 28846700, 2017). "However, inhibiting CXCR4 with CTCE-9908, a drug approved by FDA for osteosarcoma, inhibited spleen, liver, and lymph node metastasis of PCa cells, indicating CXCR4 may be a common metastatic factor, rather than one that is bone specific." (PMID 25566502, 2014). "A direct connection between CXCR4 and the IGF system has not been demonstrated so far in osteosarcoma but downstream effectors of RTK affect CXCR4 expression in this tumor." (PMID 34440844, 2021). "In the present study, we observed that the expression of CXCR2, CXCR4, and CXCR5 were not correlated with the prognosis, but CXCR3 low expression was correlated with poor prognosis in osteosarcoma." (PMID 31696204, 2019). "Although fibroblastic osteosarcoma specimen OS-7 did not exhibit the readily discernable spatial differences in CXCR4, CXCL12, and MIF expression observed in the other specimens, ligand-receptor analysis did indeed provide evidence of regional differences in the CXCR4 signaling axis." (PMID 39896512, 2025).
AIDS (103 papers, 2005 to 2025). A syndrome resulting from the acquired deficiency of cellular immunity caused by the human immunodeficiency virus (HIV). "The CXCR4 inhibitor AMD3100 was originally developed for treating acquired immune deficiency syndrome (AIDS)." (PMID 35008248, 2021). "Studies have linked this subtype to a high proportion of CXCR4-tropic virus, hastening AIDS development and immune failure." (PMID 38994006, 2024). "Patients had a higher HIV viral load at diagnosis, they presented with AIDS within three years, and the variant was observed to be more frequently CXCR4-tropic and had better fitness of the protease." (PMID 31947872, 2020). "In particular, virus strains utilizing CXCR4 or both co-receptors are associated with a higher incidence of AIDS development." (PMID 30717348, 2019). "SDF1, the unique ligand of HIV coreceptor CXCR4 was reported to be associated with host susceptibility and AIDS progression but the conclusions were controversial." (PMID 29420545, 2018). "CRF14 has been associated to a predominance of CXCR4 tropism, which usually leads to faster AIDS onset." (PMID 28912478, 2017). "It is associated with reduced levels of CXCR4 in PBMCs from healthy donors; and with a delayed progression to AIDS or death." (PMID 24167505, 2013). "During 30 years of research on human immunodeficiency virus (HIV), our knowledge of its cellular receptors - CD4, CCR5 and CXCR4 - has illuminated aspects of the pathogenesis of the acquired immune deficiency syndrome (AIDS)." (PMID 23692808, 2013). "In late disease, CXCR4-using (X4) variants can be isolated from up to 50% of AIDS patients and are associated with a more rapid loss of CD4+ T-cells and faster disease progression." (PMID 22420378, 2012). "In line with the effect of the BSSL genotype on progression to AIDS, we observed a delay in the emergence of CXCR4-using HIV-1 variants is associated with the HH genotype." (PMID 22412885, 2012). "For example, in patients infected with subtype-B HIV-1, variants that use CXCR4 can be isolated from approximately half of the patients who have developed AIDS." (PMID 21284904, 2011). "Viral phenotypes related to clinical progression include the CXCR4 or CCR5 coreceptor usage; with CXCR4 use associated with more rapid progression to AIDS." (PMID 20552027, 2010). "HIV-1 R5 viruses cause most of the AIDS cases worldwide and are preferentially transmitted compared to CXCR4-using viruses." (PMID 18205925, 2008). "CCR5-using (R5) viruses are mainly transmitted, while CXCR4-using (X4) variants can be isolated from up to 50% of AIDS patients in subtype B infections and correlate with a more rapid loss of CD4+ T-cells and faster disease progression." (PMID 18205925, 2008). "HIV-1 strains that can use both CCR5 and CXCR4 (R5-X4 strains) often emerge, but their roles in pathogenesis of acquired immune deficiency syndrome (AIDS) remain to be elucidated." (PMID 18577234, 2008). "The appearance of CXCR4-tropic viruses is associated with the progression to AIDS." (PMID 33805985, 2021). "However, variants able to use CXCR4 (X4 viruses) or both CCR5 and CXCR4 (R5X4 viruses) can be isolated from approximately 40% to 50% of HIV positive individuals as the infection progresses to AIDS." (PMID 34122453, 2021). "Human immunodeficiency virus (HIV) causes acquired immune deficiency syndrome (AIDS) and enters the host cell via CD4 and either CC-chemokine receptor 5 (CCR) or CXC-chemokine receptor 4 (CXCR4)." (PMID 33396586, 2020). "However, once HIV infection is established, dual tropic and CXCR4-preferring viruses slowly evolve from macrophage-tropic HIV viruses as an indication of progression to AIDS and HIV-associated dementia." (PMID 30052626, 2018). "CXCR4-using variants eventually arise in up to 50% of patients infected with subtypes B or D. This transition to efficient CXCR4 utilization is often co-incident with progression to AIDS." (PMID 26083631, 2015).
AIDS (continued). "While not commonly used by transmitted viruses, CXCR4 also plays an important role in HIV pathogenesis as up to half of late-stage infected individuals harbor viruses capable of using CXCR4 to enter cells, and the presence of these viruses is associated with a more rapid progression to AIDS." (PMID 24662607, 2014). "HIV-1, the causative agent of the Acquired Immunodeficiency Syndrome, AIDS, infects target cells that present the entry receptors and co-receptors CD4 and CXCR4/CCR5 on their surface." (PMID 23227982, 2012). "Despite constraints on the mutational pathways that lead from CCR5- to CXCR4-usage and the low fitness of transitional intermediate variants, CXCR4-using viruses eventually appear in about 50% of subtype B HIV-1-infected individuals prior to the development of AIDS." (PMID 21731496, 2011). "In approximately half of the individuals infected with subtype B HIV-1, CXCR4-using (X4) variants evolve from R5 viruses during the asymptomatic phase of infection, and their emergence coincides with an accelerated progression to AIDS." (PMID 21731496, 2011). "CXCR4 has been extensively investigated and implicated in several diseases besides WHIM syndrome including acquired immunodeficiency syndrome (AIDS), where it serves as a coreceptor for human immunodeficiency virus (HIV), and cancer, where it has a role in metastasis." (PMID 34973340, 2022). "CXCR4 is the main coreceptor of HIV-1 in the later stages of infection, that leads to a decrease in CD4 cell count and is linked to a higher chance of advancing to the acquired immune deficiency syndrome (AIDS)." (PMID 34684878, 2021). "The type of co-receptor used by the virus, the so-called co-receptor tropism, has a prognostic value, since patients with a CXCR4-tropic virus (“X4 virus”) progress faster to Acquired Immunodeficiency Syndrome (AIDS) compared to patients with a CCR5-tropic virus (“R5 virus”)." (PMID 20419152, 2010). "Recent evidence suggests that CXCR4 antagonists slow down disease progression and potentially delay the onset of AIDs." (PMID 40075611, 2025). "The chemokine receptor CXCR4 is implicated in multiple diseases including inflammatory disorders, cancer growth and metastasis, and HIV/AIDS." (PMID 38439632, 2024). "Major commonalities do persist between FIV and HIV in pathophysiology (AIDS) and dependency factor utilization, such as CXCR4 and LEDGF, and both have Vif proteins that degrade APOBEC3 proteins (39, –, 41)." (PMID 36927083, 2023). "In the field of HIV/AIDS, compounds have been described to exert antiviral activity at concentrations that preserve CXCR4 signaling." (PMID 36770826, 2023). "The only sample from which the majority of sequences were from viruses predicted to use CXCR4 (four of five sequences) was from an individual that developed AIDS (CD4+ T-cell count = 138 cells/μL, CD4% = 17) at the time-point when this sample was taken." (PMID 36366545, 2022). "Similar to HIV-1 infections, viruses with CXCR4 use have been isolated from HIV-2-infected individuals with low CD4+ T-cell counts or clinical symptoms of AIDS." (PMID 36366545, 2022). "Specifically, in the early stages of infection, the virus uses CXCR4 for viral entry; subsequently, it takes advantage of CXR4 to promote Acquired Immune Deficiency Syndrome (AIDS) progression." (PMID 36293358, 2022). "CXCR4-using viruses are more often than R5-viruses associated with accelerated depletion of CD4TL and progression to AIDS." (PMID 33872329, 2021). "CXCR4-using viruses are considered more pathogenic, linked to accelerated depletion of CD4TL and progression to AIDS." (PMID 33872329, 2021). "The chemokine receptor CXCR4 was identified as an HIV-1 co-receptor and mediator of cell entry soon after the identification of this pathogen as the causative agent of AIDS." (PMID 33339432, 2020). "HIV-1 89.6 is a dual CXCR4/CCR5-tropic HIV molecular clone isolated from the peripheral blood of an AIDS patient." (PMID 32119644, 2020).